IL1RN (interleukin 1 receptor antagonist)
Diseases named in the same sentence as IL1RN in open-access papers (continued):
Sharing a sentence is not in itself a finding about the gene and the disease.
tumor (continued). "The objective of this study was to investigate IL1RN expression in normal and PTC tissues by performing bioinformatics analysis to elucidate its possible role in tumor progression." (PMID 33238942, 2020). "Objective response rate (complete or partial response) was significantly correlated to tumor microenvironment-related SNPs concerning CCL2, NOS3, IL1RN, IL12B, CXCR3, and IL6R genes." (PMID 32733486, 2020). "Based on these results, we propose a model that some tumor cells, like TRAMP-C1, suppress the inflammatory signaling in tumor microenvironment through the inhibitory effects of IL1RN." (PMID 32244522, 2020). "Thus, the role of the IL1RN in tumor biology remains unclear." (PMID 33322099, 2020). "We found that the proteins were significantly modified compared to the control, and immune-related genes such as IL36RN, IL1RN, and NFKBIA were regulated by DAC, which suggested that the immunogenicity of the tumor cell was improved." (PMID 29622799, 2019). "Eight of these immune response genes (SPP1, PDPN, IL1RN, IL6, CCL8, MDK, IRF7, and HRH4) were expressed between 1.25–1.59 fold higher in the microglia/macrophage enriched population compared to bulk tumor." (PMID 22937035, 2012). "Among down-regulated genes in tumor, KRT4 showed the highest order of magnitude (530-fold) and IL1RN the lowest (9-fold)." (PMID 19835631, 2009). "When optimized cut-off values were selected, the single expression level of IL1RN, MAL or MMP1 correctly predicted the tumor or normal nature of tissue samples in, respectively, 87, 86 and 88 cases out of the 92 tested samples." (PMID 19835631, 2009). "These levels were lower in tumor than in normal samples for KRT4, KRT13, IL1RN, MAL and TGM3 (Wilcoxon test for paired data, p < 0.001)." (PMID 19835631, 2009). "Furthermore, several other marker genes that are known to support tumor growth and creating an immune suppressive environment like IL6, IL10, C1QA, interleukin‐1 receptor antagonist (IL1RN), and KYNU were highly expressed in our Tri culture condition." (PMID 40056038, 2025). "IL1RN and IL10 have anti-inflammatory functions, IL1 promotes inflammation, carcinogenesis and anti-tumor immunity, IL6 is pro-tumoral by activating carcinogenesis and tumor outgrowth, and IL10 promotes cytotoxicity but inhibits anti-tumor activities." (PMID 37465363, 2023). "Major initiators of tumor inflammation such as CCL2, CXCL1, CXCL2, CXCL11, CSF1, LTB, and TNFSF10 were found to increase in both cell lines, while inflammation suppressors like IL13and IL1RN were decreased." (PMID 36831395, 2023). "In CRC, we found that Anaerolineae and TM7—oral microbes that also inhabit the human gastrointestinal tract, and are known to promote oral and colorectal tumorigenesis—are negatively correlated with host genes enriched in the tumour-promoting interleukin-10 signalling pathway, such CXCL8 and IL1RN." (PMID 35577971, 2022). "Furthermore, 15 seed genes were further characterized to identify initially the potential of IL1RN and PRRX1 as markers of tumor immune infiltration in CRC tissues." (PMID 36483329, 2022). "In addition, this disparity became more obvious with the progression of tumor stage, suggesting a potential function of IL1RN and PRRX1 in tumor development and migration." (PMID 36483329, 2022). "Additionally, the characteristic expression profile of this cell subgroup included multiple myeloid cell activation markers, such as IL1RN, CXCL8, CCL20, and the chemokines CCL3 and SPP1, indicating the activated state of myeloid cells in the tumour microenvironment." (PMID 40539065, 2025). "Since tumor type-specific microenvironments might be determined by multiple mechanisms, it is possible that LLC cells stimulate stroma and immune cells to overcome the anti-inflammatory effects of IL1RN." (PMID 32244522, 2020). "The source of IL1RN in the TRAMP-C1-derived tumors was likely from both the MSCs and M2-macrophages, but not tumor cells per se." (PMID 36672395, 2023).
tumor (continued). "IL1RN inhibits PGE2, IL-6 production and MM cell growth, FTH1 is a favorable prognostic protein but is not really known to contribute to anti-tumor response and the death receptor FAS induces apoptosis in a large number of cell types." (PMID 26036313, 2015). "Using C.M. collected from MSCs treated with siRNA targeting either IL1RN or CCL2, we also observed the inhibition of proliferation; however, the mechanism was not likely due to the IL-28 related pathway, since the tumor cells were not sensitive to exogenous IL-28 at high concentrations." (PMID 36672395, 2023). "We also examined whether IL1RN can be regulated by pro-inflammatory signals and found that TRAMP-C1 cell line treated with either LPS or TNFα did not affect IL1RN expression, supporting that the anti-inflammatory effects in tumor tissues are due to those recruited TILs, but not TRAMP-C1 cells." (PMID 32244522, 2020).
infection (42 papers, 2008 to 2025). The state of being infected such as from the introduction of a foreign agent such as serum, vaccine, antigenic substance or organism. "The downregulated genes associated with the ADM pathway included MAPKs, PLCs, the PIK3R2, the guanylate cyclase C, implicated in infection and inflammation control and the IL1RN, which encodes the anti-inflammatory protein IL-1Ra." (PMID 38241313, 2024). "The minor allele of rs4252961 in IL1RN was associated with lower plasma IL-1ra and was related to a decreased risk of infections other than pneumonia." (PMID 36005151, 2022). "During early infection, transcriptional factors associated with negative regulation of immune function, including IL1RN, SOCS1, and TRIM24 were downregulated." (PMID 33806942, 2021). "The level of mRNA encoding 4 interleukins (Il10, Il11, Il1rn, Il1a) was increased and 1 interleukin (Il18) decreased in vaginal tissue collected at 35 days post-infection." (PMID 26779389, 2015). "Among the differentially expressed genes, four genes, Il1, Il1rn, Ptges, and Ptges2, showed marked up regulation in susceptible strains, while showed no change or slight decrease in levels in resistant strains post-infection." (PMID 18421376, 2008). "IL-1RN gene polymorphisms affect IL-1ra level and thus may influence the risk of infection." (PMID 32454789, 2020). "Other pro-inflammatory factors like IRF5, IL-12B, IL-1RN, IL-22, IL-8, and IL-33 significantly increased at 48 hpi in weaned piglets compared to newborn piglets after infection." (PMID 40589734, 2025). "Violin plots show that Kp52145 infection increased the levels of the M(Kp) markers arg1, il10, chi3l1, ido, pparγ, mrc1, nos2, isg56 and il1rn (Fig EV5A–E)." (PMID 36337046, 2022). "At 24 h this ratio is lower for every bacterial strain in the presence of IgG, which infers that the IgG antibodies elevated mRNA expression of anti-inflammatory IL-1RN gene at this post-infection time." (PMID 33968026, 2021). "b) In SP-A2 (1A0) male, interleukin-1 (IL-1) and IL1 receptor antagonist (IL1RN) get indirectly activated at 6 h post-infection." (PMID 32670284, 2020). "IL-1 receptor antagonist (Il-1rn) expression is also increased 48 hours after infection in transgenic animals." (PMID 27973535, 2016). "The Il1rn gene, strongly upregulated by 4T1 cancer cells, remained unaffected by infection." (PMID 40547518, 2025). "In addition, anti-inflammatory IL-1RA was significantly higher at some time points after infection with SARS-CoV-2 (expressed by IL-1RN gene in SupraBC-Club and basal cells in tracheobronchial ALI tissues, and ATI and ATII cells in alveolar ALI tissues)." (PMID 35962146, 2022). "Infection led to robust induction of chemokine and interleukin genes, including Il1b, Il6, Ccl2, Ccl3, Ccl4, Ccl7, Cxcl1, Cxcl2, Cxcl5, Cxcl9, and Cxcl10, and related receptor genes, including Ccr1, Ccr4, Ccr5, Ccr5, Ccr7, Cxcr2, Cxcr5, Il1r2, and Il1rn." (PMID 35487885, 2022). "IL1RN (IL-1 receptor antagonist, IL-1Ra), a known negative regulator of IL-1 signaling facilitates infection and is associated with frequent cycles of mitochondrial damage-repair in sepsis." (PMID 34031475, 2021). "Genotyping of IL-1RN (VNTR) and IL-1β 511C/T polymorphism may be beneficial to predict the immune defense against infection and a prolonged Th1 cell-mediated immune response." (PMID 29849489, 2018). "As infection progressed, we detected a robust upregulation of genes encoding cytokines and chemokines (CCL2, CCL3, IL1B, CXCR1, IL1RN) as well as granulocyte associated transcripts (TLRs 1-4, SPI1, S100A8, S100A9, CD177), which correlated with the higher numbers of granulocytes 5 DPI." (PMID 28852031, 2017). "Considering the time course of immune activation, we found that E. coli modulated the mRNA abundance from only 3 loci during the first h of infection including the upregulated expression IL1RN (interleukin 1 receptor antagonist) known to antagonize IL1 signaling." (PMID 28684793, 2017).
infection (continued). "Hence, the genes Ccl2, Ch25 h, Ifit3, Il1rn, Il6, Parp14, Ptx3, and Socs3 can be defined as a common core of genes expressed early in response to local infection and inflammation caused by Gram-negative stimuli." (PMID 21338499, 2011). "In the present study at 6 h post-infection, IPA showed indirect activation of both IL1 and IL1RN in AM of SP-A2 (1A0) male." (PMID 32670284, 2020). "Interleukin-1 receptor antagonist (IL-1Ra) is known as an early inhibitory cytokine, which potentially participates in PRRSV-induced immunosuppression during the early phase of infection." (PMID 30972072, 2019). "IL1RN, MAPK1, TRIM24 and NKX2-3 were inhibited during infection in both classes, with significantly more inhibition in the ΔNF class relative to the ΔEF class." (PMID 27506615, 2016). "Similar to this study, we observed significant up-regulation chemokines and cytokines, such as CCL3, CXCL10, IL1RN, IL6 and TNF, throughout infection." (PMID 25079789, 2014). "FCPLJ treatment downregulated several inflammatory cytokine genes in the liver, including CCL6/MRP-1, CCL8/MCP-2, CCL12/MCP-5, CCL17/TARC, IL1R1, IL1RN/IL1Ra, NAMPT/PBEF1, and PF4/CXCL4, indicating its potential role in mitigating inflammation during infection." (PMID 40007026, 2025). "Our data suggest that BM CD63+ stromal cells contribute to inflammation with Il1b expression in the absence of IL-1rn with no need of injury or infection sensing." (PMID 36596811, 2023). "We observed a temporal increase in expression of the Type I IFN response genes Il1rn, Ifit2, Ifit1 and Ifih1 (data not shown) upon infection." (PMID 34603294, 2021). "In our analysis, we observe that a subset of these cytokines reported to be present in the serum also show transcriptional upregulations in PBMCs by 4 days post-infection (IL6, IL1B, IL1RN, CCL8, CXCL10) and by 7 days post-infection (CCL2, CCL3, CSF1, TNF, CXCL1, FAS and CXCL8)." (PMID 27595844, 2016). "Functionally, loss of IL-1rn in vivo biases HSC differentiation into the myeloid lineage and induces excess myeloid lineage expansion reminiscent of early hematological disease, through IL-1r1 and IL-1β overactivation in HSC but not IL-1α, in the absence of injury or infection." (PMID 36596811, 2023). "Based on this calculation, the difference in Il1rn expression between LFD and HFD would actually be larger rather than smaller after infection." (PMID 19865485, 2009).
cancer (28 papers, 2002 to 2025). A tumor composed of atypical neoplastic, often pleomorphic cells that invade other tissues. "Various studies have highlighted the significant association between IL1RN expression and poor cancer prognosis; however, the results of these studies are conflicting." (PMID 33238942, 2020). "Of the 33 cancer types tested, 12 cancer types were associated with significantly increased IL1RN expression." (PMID 33238942, 2020). "In addition to the upregulated Il11 and Il1rn, which were notably lowly transcribed in early passage deermouse cells in comparison to mouse cells, two cancer-associated genes, Brca1 and Myc, were more highly transcribed in P47 than in P4 cells." (PMID 41262241, 2025). "The underlying mechanism of IL1RN in cancer development and progression is complicated and unclear." (PMID 33238942, 2020). "Bacterial/virus affection status Subgroup analysis of IL1RN VNTR polymorphism to cancer risk." (PMID 23049925, 2012). "Once the balance between IL1RN and IL-1 is disturbed, physiological disorders of the human body would lead to the higher incidence of many cancers." (PMID 39310253, 2024). "Interleukin-1 receptor antagonist (IL-1Ra) is a natural anti-inflammatory cytokine; however, its contribution to cancer pathogenesis and immunosuppression remains elusive." (PMID 37563620, 2023). "Interleukin-1 receptor antagonist (IL-1RA), a member of the IL-1 family, has diverse roles in cancer development." (PMID 37461111, 2023). "The data showed that the degree of IL1RN DNA methylation was lower in carcinoma tissues than in normal tissues (P < 0.0001)." (PMID 33238942, 2020). "Of those modulated genes, SPP1, IL1RN, IL1A, TNFSF13B, OSM, and CSF3 had the most clinical relevance, as their high expression was associated with poor cancer patient overall survival." (PMID 31022845, 2019). "IL1RN has been described as an inhibitor of inflammation, and IL1RN gene expression has been reported in advanced stages of cancer that could be related to an evasion of the immune response, a mechanism that some cancers use to continue their progression." (PMID 39201290, 2024). "The results showed that the expression levels of IL1RN varied greatly in different cancer types." (PMID 33238942, 2020). "Finally, IL1RN shows superior prognostic value for various cancers according to the pancancer analysis." (PMID 33238942, 2020). "Interleukin-1 receptor antagonist (IL1RN) has been reported as a biomarker of many cancers." (PMID 33238942, 2020). "The balance between IL1RN and IL-1 plays a crucial role in many diseases, including cancer." (PMID 33238942, 2020). "To investigate whether IL1RN has broad value, we performed a series of studies on IL1RN across all cancers." (PMID 33238942, 2020). "Similarly, high expression of the IL1RN correlates with either better or worse cancer prognosis." (PMID 39201290, 2024). "IL1RN was the hub gene with the most edges found in this study, despite the fact that its overall survival or disease-free survival showed differences between the cancer-bearing and normal populations, but online databases suggested that the results were not statistically significant." (PMID 36483329, 2022). "After identifying IL1RN as a potential modulator of the invasive capacity of cancer cells, we used ectopic expression in T24 cells to address the question of whether IL1RA expression itself is sufficient to impair the migration and invasion capacity of BC cells." (PMID 34070905, 2021). "Of these, ALDOB, WNT11, MSLN, RAC3, and IL1RN have known roles in CRC, FBLX16 has known roles in other cancers, and SLC38A11 and WBSCR27 are relatively uncharacterized." (PMID 38680862, 2024).
cancer (continued). "Thus, high IL1RN expression could have either good or bad cancer prognosis." (PMID 39201290, 2024). "The most up-regulated genes in U87 cells were interleukins and receptors (IL1A, IL13RA2, IL1RN), CT45A5 from the cancer/testis (CT) family of antigens, and the cytoplasmic transporter ATP6V0D2." (PMID 25481245, 2014). "Our earlier studies demonstrated that TILs, not cancer cells or peripheral blood mononuclear cells in circulation, were the primary source for expressing and secreting the IL1RN in the TRAMP-C1-derived TME." (PMID 33322099, 2020). "Furthermore, the significant positive correlation in the co-expression of IL-1β and IL-1RN in READ suggests that both genes, although overexpressed in cancer, interact in an inflammatory cycle, as previously demonstrated, where a 1β/1RN axis regulates various aspects of CRC via autophagy." (PMID 39766795, 2024). "From a clinical point of view, IL1RN, MAL and TGM3 were not clearly identified as potential HNSCC markers, while few data have been published concerning the implication of FN1, KRT, MMP1, PLAU and SPARC in this type of cancer." (PMID 19835631, 2009).
inflammation (4 papers, 2022 to 2025). Aberrant reaction of the microcirculation characterized by movement of fluid and leukocytes from the blood into extravascular tissues. "Furthermore, TYMP1 has also been described to possess an anti-apoptotic effect, whereas IL1RN has been described as an anti-inflammatory antagonist of the interleukin-1 family of proinflammatory cytokines protecting against immune dysregulation and uncontrolled systemic inflammation." (PMID 37947626, 2023). "Looking at clinical manifestations, for instance, the CFA stimulation model and IL1RN deficiency/Tsc2 KO models may be more suitable for studying chronic and arthritic subtypes of SJIA, while the repeated TLR-9 model may be preferable for studying lung inflammation." (PMID 36964620, 2023).
dermatitis (2 papers, 2021 to 2024). An inflammatory process affecting the skin. "Polymorphisms in human IL1RN have been associated with in vivo control of Epstein–Barr viral load, and with inflammatory bowel and skin disorders that have also been associated with the REL locus." (PMID 34707143, 2021).
hematologic malignancies (2 papers, 2020 to 2023). "Variants impacting IL-1β are reported to influence risk of IA in patients with hematologic malignancies, and following solid organ transplant; the genes harboring risk variants include IL1A, IL1B, IL1RA, and IL1RN." (PMID 32185141, 2020). "IL-1rn-KO mice develop an IL-1β-induced phenotype reminiscent of early hematopoietic disease." (PMID 36596811, 2023).
immune disorders (2 papers, 2023 to 2025). "One such immune disorder is the deficiency of the IL-1 receptor antagonist, a rare but severe autoinflammatory disease characterized by mutations in the IL1RN gene." (PMID 40668918, 2025). "IL1RN DNA methylation editing alters myeloid cell fate and immune responses, revealing epigenetic drivers of immune diseases." (PMID 40668918, 2025). "Overactivity in this pathway leads to various immune disorders that can be managed by treating patients with a recombinant form of IL-1RN known as anakinra." (PMID 40668918, 2025).
head and neck tumors (1 paper, 2024). "In this study, it was found that IL-1α, IL-1β, IL1R1, IL1RL1, IL1F10, IL33, CASP1, and AIM2 were highly expressed in head and neck tumors, while IL1RN, IL1RAPL1, IL1RAPL2, IL18BP, IL18R1, and IL18RAP were low in expressed, which is consistent with previous literature." (PMID 39461030, 2024).
IL1RN also shares sentences with these, for which no sentence is quoted: chronic periodontitis (4 papers); Crohn disease (4); bacterial infections (3); infectious disease (3); acne (2); adenocarcinoma (2); allergies (2); chronic infantile neurological cutaneous articular syndrome (2); dental caries (2); encephalitis (2); familial Mediterranean fever (2); Hypertension (2); hypophysitis (2); idiopathic pulmonary fibrosis (2); leukemia (2); multiple myeloma (2); myositis (2); Peptic ulcer (2); primary biliary cholangitis (2); scleroderma (2); synovitis (2); systemic lupus erythematosus (2); abdominal aortic aneurysm (1); actinic keratosis (1); acute myeloid leukemia (1); acute pancreatitis (1); acute respiratory distress syndrome (1); adenoma (1); aggressive periodontitis (1); allergic asthma (1).
A further 67 diseases each share a sentence with IL1RN in 1 paper.